PDGFRA (platelet derived growth factor receptor alpha)
Diseases named in the same sentence as PDGFRA in open-access papers (continued):
Sharing a sentence is not in itself a finding about the gene and the disease.
tumor (continued). "The results showed that the growth factor LR interacts with PDGFB : PDGFRA, IGFBP4:FZD8, and TGFB1:SDC2 with TAMs and tumor vascular cells." (PMID 35664733, 2022). "Analysis of scRNA-seq data from all 28 tumors in the dataset showed that elevated CD73 expression was principally focused in two discrete clusters of AC-like and OPC-like tumor cells, which exhibited high expression of EGFR and PDGFRA, respectively." (PMID 35973991, 2022). "Using our gene–gene fusion database, ChiTaRS 5.0, we identified gene–gene fusions in cfDNA and tumour DNA, such as KDR–PDGFRA and NCDN–PDGFRA, which correspond to previously reported alterations of PDGFRA in GBM (44% of all samples)." (PMID 34875133, 2022). "Real time PCR was performed to provide an initial assessment of mRNA transcript expression of the RTKs PDGFRa, PDGFRb, VEGFR2, and KIT in primary UC tumor samples (N = 9) and established canine UC cell lines (N = 5)." (PMID 34600548, 2021). "While transcript for PDGFRα, PDGFRβ, VEGFR2 and KIT was detected in all tumor samples and UC cell lines, the pattern of expression was variable." (PMID 34600548, 2021). "Sunitinib, a MKI targeting VEGFR1,2,3, Kit, PDGFRA/B, FLT-3 and RET has also shown efficacy in the reduction of the primary tumor proliferation and the tumor vasculature in cell-derived osteosarcoma mouse models." (PMID 34069999, 2021). "Anlotinib, as a new multi-target RTK inhibitor, has a significant anti-tumor activity for VEGFR signals and inhibition for FGFR 1–3, PDGFRα, and c-kit." (PMID 34094958, 2021). "The patients with high KDR, PDGFRA, LRP1, COL1A2, and SAMD9 expression had shorter OS (log-rank test, P < 0.05), indicating that tumor antigens were critical for the progression of diffuse gliomas." (PMID 34815785, 2021). "This translocation up-regulates the expression of PDGFRα, VEGF and other proteins related to tumor and vascular cell proliferation." (PMID 33525546, 2021). "Indeed, overexpression of constitutively active PDGFRA in cultured mouse neural stem cells arrested their differentiation at the O4+ pre-oligodendrocyte stage, confirming that failure to switch off PDGFRA signalling plays an important role in preventing terminal differentiation of tumour cells." (PMID 33846316, 2021). "Previously, intra-tumour heterogeneity was demonstrated at the level of EGFR, PDGFRA, and MET using fluorescent in situ hybridisation (FISH)." (PMID 33477674, 2021). "Analysis of a tissue microarray (TMA) identified both PDGFRA expression and basal SFK phosphorylation as detectable in the majority of normal glial cells in healthy brain tissue as well as in GBM tumours." (PMID 33478100, 2021). "Transcript for PDGFRa, PDGFRb, VEGFR2, and KIT was detectable in all of the primary UC tumor samples and UC cell lines although this was present at varying degrees." (PMID 34600548, 2021). "Analysing 128 murine tumours, we identified 5–6 main CAF populations and numerous minor ones based on the analysis of αSMA, FAPα, PDGFRα, PDGFRβ, CD26, and PDPN." (PMID 34016130, 2021). "We observed that in the primary tumor samples evaluated, the profile of RTK activation in UC cells lines was similar to that found in tumors with evidence of PDGFRα and PDGFRβ phosphorylation present in only 25% of UC cell lines evaluated." (PMID 34600548, 2021). "Here we displayed that ASP4132 treatment similarly induced PDGFRα-EGFR protein degradation and inhibited downstream Akt activation in NSCLC cells and xenograft tumor tissues." (PMID 33824293, 2021). "Immunofluorescence of PDGFRα and angiogenic marker CD31 in tumor tissues revealed an increase in GL261-PDGF-D vs GL261-vector tissues." (PMID 34470658, 2021). "Unlike the parent molecule, however, p700 exhibits a broader binding specificity for other growth factor receptors such as VEGFR1, VEGFR3, PDGFRα, FGFR1, FDFR2α, FDFR3 and FDFR4, all of which are highly expressed in tumours or tumour vasculature." (PMID 33504102, 2021).
tumor (continued). "PDGFRA is up-regulated in BLCA tissues, which is significantly related to tumor prognosis and can be used as a prognostic marker of BLCA." (PMID 33888644, 2021). "Immunohistological assays were applied to validate the expression of CXCL12, PDGFRA and VIM in normal and tumor tissues." (PMID 34801033, 2021). "Numerous studies into the molecular events driving GBM highlight the central role played by the Epidermal Growth Factor Receptor (EGFR), as well as the Platelet-derived Growth Factor Receptors PDGFRA and PDGFRB in tumor initiation and progression." (PMID 34830952, 2021). "A possible reason is the wide range of tumor cell targets affected (VEGF, VEGFR1–3, FGFR1–4, PDGFRα, KIT, and RET)." (PMID 34630336, 2021). "This evidence shows that mutant KIT and PDGFRA can be detected and quantified in plasma of GIST patients, also with a predilection for patients with high tumor burden." (PMID 32024476, 2020). "It should be noted that one interaction involved two different isoforms of the platelet-derived growth factor receptor alpha (PDGFRA) in the normal and tumor cells, a membrane form in HEK 293 cells and a secreted form in HCT 116 cells." (PMID 33383846, 2020). "The GEP and CNA pattern for the EGFR, CDK4, MDM4, and PDGFRA genes was available in 83/83, 68/83, 68/83, and 68/83 GBM tumor samples evaluated, respectively." (PMID 31963499, 2020). "Amplifications of EGFR and gain of chromosomes 19 and 20 were strongly prevalent in RTK II, and PDGFRA, CDK4 and MDM2 or MDM4 amplifications were more frequent in RTK I tumours." (PMID 33339831, 2020). "Eosinophilia-specific PDGFRA-fusion with FOXP1 disrupts this gene, supporting tumor suppressor activity in this malignancy." (PMID 33048949, 2020). "We provide the first direct evidence that GSCs derived from different regions of the same tumor may differ markedly in the expression levels of pleiotropic factors playing key roles in defining the transcriptional and cellular landscapes in GBs (TGFβ, PDGFRA, CD133)." (PMID 32102350, 2020). "Of these biopsies, 95 samples from 25 patients contained adequate tumour and/or DNA content for EGFR and PDGFRA amplification status to be determined successfully through aCGH analysis." (PMID 33120534, 2020). "In high PDIA3 expression samples, frequently amplified genomic peaks were detected in oncogenic drivers, including PDGFRA, EGFR and CDK4; in addition, tumor suppressor genes, such as CDKN2A/CDKN2B and PTEN were observed a deletion peak." (PMID 32687065, 2020). "This study comprehensively characterized 9 MGs and adenocarcinomas present in the same surgical resection specimen by analyzing the c-KIT/PDGFRα status and EBV/MSI status on both tumor types." (PMID 33335133, 2020). "Validation of these findings in patient samples of skin SCCs shows a strong correlation between the expression of SDF1, PDGFRA, and PDGFRB, which is upregulated, along CXCR4 in tumor cells of advanced SCCs." (PMID 30874597, 2019). "Ex vivo assays performed on tumor cell cultures exposed to a TKI for two hours from a single patient case with IS, demonstrated a dose-response in decreasing PDGFRA phosphorylation confirmed by western blotting." (PMID 31480474, 2019). "Of note, PDGFRA and KIT were expressed at relatively low levels in tumor tissue and higher in healthy kidney tissue." (PMID 30881919, 2019). "Strong induction of PDGFRα/β, as well as SDF-1 and CXCR4, was detected in tumor cells of patient PD/S-SCCs, and the inhibition of PDGFR signaling downregulated SDF-1 expression and vice versa." (PMID 30874597, 2019). "Sunitinib has direct anti-tumor effects via binding the unactivated conformation of KIT and via platelet-derived growth factor receptor alpha polypeptide (PDGFRA) inhibition." (PMID 29544452, 2018).
tumor (continued). "As the PDGF–PDGFR system is the best-characterized signaling pathway in pericyte recruitment in angiogenic vessels, we investigated the effects of PDGFRα and PDGFRβ specific blockades in pericyte recruitment in FGF2+ tumor models." (PMID 29423271, 2018). "If the goal is targeting tumor vessels, then VEGFR2 and PDGFRα are highly targetable: >70% target cells have > 6,000 VEGFR2 or PDGFRα/cell plasma membrane with QE = 0.20 or 0.32, respectively." (PMID 30050899, 2018). "Another multi-kinase inhibitor sunitinib, an anti-PDGFRα/β, VEGFR1/2/3, KIT, FLT3, CSF- b1R and RET, has been shown to decrease primary tumor proliferation and reduce tumor vasculature in cell-derived intratibial OS model in SCID mice." (PMID 29520051, 2018). "In contrast, more than half of the tumours with high PDGF-CC and high PDGFRα expression in tumour or stromal cells displayed low PDGFRβ." (PMID 29380207, 2018). "Lenvatinib is an oral, multitargeted TKI of VEGFR1-VEGFR3, RET, fibroblast growth factor receptors 1–4 (FGFR1-FGFR4), PDGFRα, and v-kit Hardy-Zuckerman 4 feline sarcoma viral oncogene homolog (KIT) signaling networks involved in tumor angiogenesis." (PMID 30619094, 2018). "Hepatocytes expressing dominant-negative PDGFRα revealed decreased TGF-β-induced migration and tumor formation." (PMID 30509307, 2018). "For example, Src family kinases HCK, FRK and LYN are onco-homologs of PDGFRA/KIT, which interact with both PDGFRA and KIT as downstream effectors and play critical roles in tumor cell proliferation and survival." (PMID 29844492, 2018). "Forty-one (8%) of primary tumours displayed a high expression of both PDGFRα in tumour cells and PDGF-CC, 63 (13%) of PDGFRα in stromal cells and PDGF-CC, and 36 (7%) of PDGFRβ in stromal cells and PDGF-CC." (PMID 29380207, 2018). "Using the monoclonal 6B3, we determined the expression pattern for PDGF-CC in different human primary tumours and control tissues, and explored its ability to neutralize PDGF-CC-induced phosphorylation of PDGFRα." (PMID 30052660, 2018). "Concomitant PDGFRα and PDGF-CC expression varied markedly over the molecular subtypes where the TNBC displayed co-expression in 59% of the tumours, whereas the luminal subtypes only displayed co-expression in 5% (Luminal A) to 19% (Luminal B HER2+)." (PMID 29380207, 2018). "Importantly, western blot analyses showed that along with these augmented levels of lytic gene expression, PDGFA and PDGFB correlated with prominent PDGFRA phosphorylation in tumor samples, suggesting that it could be a result of lytic induction occurring during in vivo tumorigenesis." (PMID 29985958, 2018). "Both TAS-115 and pazopanib blocked the phosphorylation of PDGFRα at Tyr754, Tyr762, Tyr849, Tyr1018, as well as the phosphorylation of downstream effectors in SYO-1 xenograft tumours." (PMID 28511645, 2017). "Instead, PDGFRα expression in HCC was accompanied by enhanced Lrat expression, suggesting increased HSC residence in tumor sites." (PMID 28465473, 2017). "Altogether, our studies demonstrate frequent disruption of MAX tumour suppressive roles during early progression of KIT-mutant, PDGFRA-mutant and NF1-mutant GISTs." (PMID 28270683, 2017). "Thus, it was considered that there was no oncogenic mutation in KIT and PDGFRA genes in this tumor." (PMID 28288693, 2017). "PDGFRA is more expressed in GBMs of the left temporal lobe than in those of the right one, whereas PDGFA expression is higher when the tumour is set on right frontal and parietal lobes as opposed to the left correspondents." (PMID 29127351, 2017).
tumor (continued). "To verify the inhibitory effects of TAS-115 and pazopanib on c-MET and PDGFRα in vivo, we administered TAS-115 (200 mg/kg) and pazopanib (100 mg/kg) orally to mice bearing Yamato-SS or SYO-1 xenograft tumours." (PMID 28511645, 2017). "IM is an inhibitor of receptor tyrosine kinases, including the stem cell factor receptor KIT and the platelet-derived growth factor receptor alpha (PDGFRA), the main drivers of tumour development in GIST." (PMID 27999655, 2016). "There is significant overlap between the H3.3-K27M subgroup and the PDGFRA-driven DIPG shown previously and between the H3.1-K27M subgroup and the tumours with a mesenchymal gene expression signature." (PMID 26399631, 2015). "In untreated tumor lysates activated PDGFRB was expressed at well detectable levels in all patient-derived xenografts and activated PDGFRA in those where its gene is amplified." (PMID 26599335, 2015). "For example, the restoration of miR-34a-5p, a tumor suppressive miRNA that simultaneously downregulates the expressions of MET, PDGFRA and CDK6, can possibly outperform any single targeted agents tailored to those targets." (PMID 26439688, 2015). "Immunohistochemical analysis of tumor tissue demonstrated upregulation of NG2, Ki67 (proliferation marker), PDGFRα, PDGFRβ and GFAP." (PMID 25987129, 2015). "Therefore, PI3K and mTOR pathway inhibitors may be relevant in a tumor with PDGFRA amplification." (PMID 26510912, 2015). "In every tumor that exhibited EGFR, PDGFRA, NTRK1, MDM2, MDM4, or CDK4 amplification, the increased copy number was contained within, or contained translocations into, a suspect chromothriptic region." (PMID 26328271, 2015). "Other alterations such as amplifications of PDGFRA, MDM2 and MDM4 were also identified as important events occurring at different steps of tumor expansion depending on the patient." (PMID 25940437, 2015). "In this tumor EGFR amplification was seen across all tumor regions, while amplification of both PDGFRA and KIT was detected in two of five regions." (PMID 25608559, 2014). "These functional properties of PDGFRα are likely to reflect its ability to engage signaling pathways, such as RAS/RAF/MEK/ERK and PI3K/AKT which play a role in tumor cell proliferation and aggressive phenotype." (PMID 24732172, 2014). "PDGFRA is collocated with FRA4B and related to tumor progression, but less reported as a pre-malignant marker." (PMID 24748104, 2014). "Our results show that gB induces p-PDGFRα and downstream signaling partners such as AKT, Src, FAK, which promote tumor cell survival and motility." (PMID 24658280, 2014). "Immunohistochemically, all tumors expressed CD117, four tumors PDGFRA, ten tumors CD34, eight tumors smooth-muscle actin, one tumor desmin, and S-100 was positive only in the intermixed dendritic cells." (PMID 22350270, 2013). "Cases with both PDGFRA and KIT amplification had a younger age of diagnosis (median = 53.7 yrs) compared with other amplified tumours (median = 60.3 yrs, p = 0.046, t test)." (PMID 23990986, 2013). "PDGFRA, KIT, and KDR genes that are located on the amplified segment 4 q12 probably play an important role in tumor biology due to their increased expression of receptors and their ligands." (PMID 23537212, 2013). "The tumor expression levels of VHL, the endothelial marker CD31, PDGFRα, VEGF and the inhibitor of apoptosis survivin (SVV) are supposed to be important markers for prognosis and outcome of patients with advanced RCC." (PMID 24086736, 2013).
tumor (continued). "Of note, tumours from the MMTV-PyMT mouse model faithfully reproduced the staining pattern of the CAF markers ASMA, PDGFRα, and FSP1 found in human tumours." (PMID 22432595, 2012). "Nevertheless, the consensus staining pattern for ASMA, PDGFRα, and FSP1 was remarkably similar to that of the tumours from MMTV-PyMT mice." (PMID 22432595, 2012). "No major differences were noted in the expression pattern of ASMA, PDGFRα, or FSP1 between early and late tumours, even though the areas of fibroblast-rich stroma increased in size over tumour progression (data not shown)." (PMID 22432595, 2012). "A significant increase in PDGFRα and its ligand PDGF-CC leading to increased phosphotyrosine-720-PDGFRα was observed in tumor-bearing KO mice (p<0.05)." (PMID 22761897, 2012). "Consistent with the in vivo findings, tumor cells expressing low levels of IGF-IR (RJ348 and RJ423) expressed high levels of PDGFRα and PDGFRβ compared to the RJ345 cells." (PMID 22070644, 2011). "When imatinib or PDGFRα blocking antibodies were used to treat RMS tumors in these mice, 50% of mice had at least a partial reduction of tumor growth." (PMID 21253475, 2011). "Although there was some inter-tumor variability, the IGF-IR-independent recurrent spindle tumors displayed an overall increase in both PDGFRα and PDGFRβ, with some tumors displaying especially high levels." (PMID 22070644, 2011). "We examined expression of the 3 receptor genes PDGFRA, KIT, and KDR, because of their central function in tumor biology and their significance as therapeutic targets." (PMID 20686603, 2010). "Five miRNAs (19b, 29a, 29b, 29c and 148a) shared 70 predicted targets, some of which (CDK6, PTEN, IGF1, FRS2, PDGFRA, PIK3R1 and MXD1) regulate cellular proliferation and tumor suppression." (PMID 20949028, 2010). "Immunohistochemical analysis showed that tumour cells express PDGFA in the cytoplasm, whereas PDGFRA was preferentially observed in the cytoplasmic compartment and rarely on membranes." (PMID 19707201, 2009). "The HSP90 family are molecular chaperones that regulate the stability of several proteins involved in tumor development (including KIT and PDGFRA); therefore, inhibition of HSP90 with pimitespib may represent an alternative treatment strategy to TKIs." (PMID 41264161, 2026). "Despite the presence of a MYCN amplification and absence of PDGFRA amplification, this tumor matched to the RTK1 subgroup." (PMID 40610013, 2026). "For somatic copy number alterations, cases with high PLK3 expression not only demonstrated significant amplification peaks for PIK3C2B, PDGFRA, EGFR, and CDK4, which are defined as oncogenic drivers, but they also showed deletion peaks for tumor-suppressor genes, such as CDKN2A and CDKN2C." (PMID 39866232, 2025). "PDGFRA activation leads to phosphorylation of PIK3R1, triggering downstream signaling cascades including calcium mobilization and activation of PKC, AKT1, HRAS/MAPK/ ERK, and STAT pathways, thereby promoting tumor growth and survival." (PMID 41426972, 2025). "However, in lobules with tumor invasion, NGFR+ stromal cells co-expressed the iCAF marker, PDGFRα, to a high extent (94%), while 22% of NGFR+ cells were positive for ASMA, and 34% for CD74." (PMID 41006303, 2025). "On immunohistochemistry, the tumor cells showed diffusely strong expression of CD34 and PDGFRA; they were sporadically positive for S-100 protein and negative for CD117, DOG-1, smooth muscle actin, Caldesmon, ALK-80, ER, CD21, Bcl-2, STAT6, CD68, CD163, CD1a, and CD207 (langerin)." (PMID 39960966, 2025). "Therefore, it is important to develop approaches targeting both Endocan-PDGFRA dependent and independent populations of GBM cells within the tumor." (PMID 39773984, 2025).